SH2B3 (SH2B adaptor protein 3)
Diseases named in the same sentence as SH2B3 in open-access papers (continued):
Sharing a sentence is not in itself a finding about the gene and the disease.
tumor (18 papers, 2015 to 2025). "SH2B3 encodes a lymphocyte adaptor protein that plays a key role in hematopoiesis and has been suggested to be a tumor suppressor." (PMID 27590521, 2016). "A frameshift mutation could result in the loss of the tumour suppressing functions of SH2B3 and may contribute to a faster progressing disease." (PMID 32857815, 2020). "In humans, SH2B3 has been called a recessive tumour suppressor gene whose mutation may lead to ALL." (PMID 32857815, 2020). "To further investigate the potential biological function of SH2B3 in GSCs’ self-renewal, we performed tumor spheres formation assay, which is a widely used assay to assess tumor stem cell’s self-renewal ability, in various GBM cell lines." (PMID 33937225, 2021). "Tumor sphere formation and colony formation ability that impaired by disruption of SH2B3 were rescued by ectopia expression of STAT3-C, indicating that STAT3-C compromised the suppressive effect of silencing of SH2B3 on GSC maintenance." (PMID 33937225, 2021). "Tumor spheres formation assay was performed, and we found that tumor spheres formation ability was dramatically repressed following silencing of SH2B3, implying that SH2B3 is essential for GBM cell growth." (PMID 33937225, 2021). "Other associations with no obvious link to kynurenine include SH2B3 (rs3184504, P = 6.05×10‐18), which is also associated with tumor occurrence and development and IDO2 (rs10085935, P = 3.33×10‐9)." (PMID 35494045, 2022). "In contrast, overexpression of SH2B3 in tumor cells remarkably decreased the tumor size and weight." (PMID 35589677, 2022). "The biological function of SH2B3 in malignancy is affected by the context with tumor types." (PMID 33937225, 2021). "We observed that knockdown of SH2B3 significantly suppressed mouse xenograft tumor growth." (PMID 33937225, 2021). "Silencing of SH2B3 markedly suppressed GBM cell tumor sphere formation ability." (PMID 33937225, 2021). "We observed that tumor spheres derived from U87, U251, and T98G cell lines were expressed higher in SH2B3 than in their corresponding monolayer cells at both protein and mRNA levels, implying that SH2B3 may play crucial roles in GSCs’ self-renewal." (PMID 33937225, 2021). "Mouse xenograft model was employed to study the functional role of SH2B3 in xenograft tumor growth." (PMID 33937225, 2021). "Although for many a function in B cells is unknown, for others (namely Arhgef1, Gadd45g, Sh2b3, and Map2k7), tumor-suppressive and/or antiproliferative activity was described." (PMID 32407433, 2020). "Lastly further analysis of the tumour suppressor role of SH2B3 in B-ALL may help to define critical signalling events elicited by increased doses of chromosome 21 gene expression in iAMP21-ALL, as well as other important sub-types with gain of wc21." (PMID 30816328, 2019). "SH2B3 plays an important role in the homeostasis of hematopoietic stem cells and lymphoid progenitors, and homozygous somatic SH2B3 mutations have previously been identified in ALL, suggesting a tumor suppressor role." (PMID 29967378, 2018). "We further explored if rs1129406 (ATF1, 12q13), rs12303082 (FAM186A, 12q13), rs6580742 (FAM186A, 12q13), rs16888728 (UTP23, 8q24) and rs3184504 (SH2B3, 12q24) genotypes affect the CRC risk differentially by sex, age at diagnosis, tumor site, stage and MSI status." (PMID 26553438, 2015). "Silencing of SH2B3 remarkably repressed GBM cell growth and tumor spheres as well as colony formation in vitro and xenograft tumor growth in vivo." (PMID 33937225, 2021).
cardiovascular diseases (12 papers, 2010 to 2026). "For instance, SH2B3 is known to play a role in immune system regulation, and its genetic variants have been linked to both cardiovascular diseases and autoimmune disorders." (PMID 40303978, 2025). "These disturbances, particularly when combined with predisposed maternal genotypes (e.g., SH2B3, eNOS variations), form a pathophysiological link between hypertensive pregnancy problems and later-life cardiovascular disease." (PMID 40649813, 2025). "Chromosome 12 contains the SH2B3 gene, associated with HT and other cardiovascular diseases." (PMID 40676916, 2025). "The purpose of this study was to investigate the effects of the SH2B3, MTHFD1L, GGCX, and ITGB3 gene variants on the efficacy of warfarin treatment and its effects on the risk of cardiovascular disorders in Jordanian patients." (PMID 32916786, 2020). "The genotypes of SH2B3, MTHFD1L, GGCX, and ITGB3 polymorphisms, plus clinical data for the participants, were evaluated to investigate their effects on the risk of cardiovascular disease and warfarin sensitivity and responsiveness during the initial phase treatment." (PMID 32916786, 2020). "Cardiovascular disease highlights CDKN2B-AS1, LPA, and SH2B3; respiratory system disease features CHRNA3; psychiatric disorders highlight APOE, APOC1." (PMID 41166152, 2026).
haematological diseases (6 papers, 2016 to 2023). "Because the coexistence of a driver clone and the acquisition of additional mutations have been identified repeatedly in hematologic malignancies, further studies are required to elucidate how SH2B3—GATA1 and NOTCH1—STAG2 mutations contribute to the pathogenesis of hypereosinophilia." (PMID 29088303, 2017).
bacterial infection (4 papers, 2012 to 2021). "Evolutionary analysis has suggested a recent selective sweep in SH2B3 in the European populations in response to possible bacterial infection." (PMID 27896059, 2013).
immune diseases (3 papers, 2016 to 2022). "According to gene ontology disease class term SH2B3 is playing a significant role in metabolic, cardio vascular and immune diseases." (PMID 35246549, 2022). "In particular, the SH2B3 locus on chromosome 12 stands out in this regard, with GWAS signals for seven immune disorders colocalizing with three trans-regulated proteins (THPO, ICAM2, CXCL11), all involved in positive regulation of immune system processes (GO:0002684)." (PMID 35078996, 2022).
heart disease (2 papers, 2018 to 2021). "Mutations in the SH2B3, the gene that encodes for LNK, have been identified in patients with a range of diseases, including blood cancers, autoimmune disorders and heart disease." (PMID 35056081, 2021).
infection (2 papers, 2014 to 2018). The state of being infected such as from the introduction of a foreign agent such as serum, vaccine, antigenic substance or organism. "Our data showing induced expression of SH2B3 in ZIKV-infected retina/retinal cells indicates that ZIKV may employ SH2B3 to evade the immune system by attenuating the inflammatory response and infiltration of innate immune cells to the site of infection." (PMID 30046058, 2018).
neurodegenerative disease (2 papers, 2013 to 2021). A disorder of the central nervous system characterized by gradual and progressive loss of neural tissue and neurologic function. "Among minor genes, SH2B3 and ATXN2 were found to be associated with both autoimmune and neurodegenerative diseases." (PMID 33544228, 2021).
SH2B3 also shares sentences with these, for which no sentence is quoted: melanoma (6 papers); disorders of thyroid (3); lymphoma (3); myelofibrosis (3); Parkinson disease (3); peripheral artery disease (3); spinocerebellar ataxia (3); vitiligo (3); developmental delay (2); Down syndrome (2); Fanconi anaemia (2); Hepatitis (2); inflammatory bowel disease (2); Insulin resistance (2); juvenile myelomonocytic leukemia (2); lymphoid leukaemia (2); spinocerebellar ataxia type 2 (2); thyroid carcinoma (2); thyroid disease (2); triple-negative breast carcinoma (2); acute coronary syndrome (1); acute myeloid leukemia (1); alopecia areata (1); Alzheimer disease (1); amyotrophic lateral sclerosis (1); anaplastic thyroid carcinoma (1); anemia (1); autoimmune Addison’s disease (1); B-cell acute lymphoblastic leukemia (1); blood cancers (1).
A further 51 diseases each share a sentence with SH2B3 in 1 paper.